USP17L23 (ubiquitin specific peptidase 17 like family member 23)
Tractability: No criterion of Open Targets' tractability assessment is met for any kind of drug.
Gene: Protein-coding gene on chromosome 4 (9,272,364 to 9,272,914, forward strand). Ensembl gene ENSG00000250913.
Subcellular location: Nucleus; Endoplasmic reticulum
Gene Ontology:
Molecular function: cysteine-type deubiquitinase activity
Biological process: protein deubiquitination
Cellular component: endoplasmic reticulum; nucleus
Homologues: Paralogues in human: USP17L11 (99% identical), USP17L15 (99% identical), USP17L17 (99% identical), USP17L18 (99% identical), USP17L20 (99% identical), USP17L22 (99% identical), USP17L19 (99% identical), USP17L24 (99% identical), USP17L25 (99% identical), USP17L26 (99% identical), USP17L27 (99% identical), USP17L28 (99% identical), and 59 more.